FGFR3 (fibroblast growth factor receptor 3)
Diseases named in the same sentence as FGFR3 in open-access papers (continued):
Sharing a sentence is not in itself a finding about the gene and the disease.
colorectal cancer (28 papers, 2003 to 2026). A primary or metastatic malignant neoplasm that affects the colon or rectum. "In colorectal tumors, mutations were possibly inactivating mutations, while decreased expression of FGFR3 was found in colorectal cancer cell lines and tumors." (PMID 23902722, 2013). "Although FGFR3 mRNA expression is downregulated in colorectal cancer, alterations mainly affected the FGFR3-IIIb splice variant, resulting in an increased IIIc/IIIb ratio predominantly in a subgroup of advanced tumours." (PMID 20234367, 2010). "Colorectal carcinoma cell lines also expressed the IIIb and IIIc variants of FGFR3 at different ratios, clearly showing FGFR3-IIIc expression in the epithelial cell compartment." (PMID 20234367, 2010). "In their experiment, PRMT5 knockdown led to decreased eIF4E and FGFR3 gene expression while PRMT5 was overexpressed in colorectal cancer cells, correlating with decreased overall patient survival." (PMID 33440687, 2021). "FGFR3, a highly conserved transmembrane tyrosine kinase receptor, overexpressed aberrantly in bladder, cervical, and colorectal cancer, suggesting that abnormal expression of FGFR3 was blamed to contribute partially to tumorigenesis." (PMID 29850625, 2018). "Our results confirm the strong anti-tumourigenic effect in vivo due to disruption of FGFR3 signalling in colorectal cancer." (PMID 20234367, 2010). "This makes FGFR3-IIIc a promising candidate target for therapeutic interventions in colorectal cancer." (PMID 20234367, 2010). "In summary, our data demonstrate that FGFR3-IIIc exerts oncogenic effects in colorectal cancer cells by promoting in vitro tumour cell growth, survival, migration and responsiveness to oncogenic FGF ligands such as FGF18." (PMID 20234367, 2010). "Our results now demonstrate that overexpression of FGFR3-IIIc stimulates tumour cell growth, whereas its blockade inhibits cell growth and induced apoptosis in colorectal cancer cells." (PMID 20234367, 2010). "Further, a reciprocal relationship between Fgfr1 and Fgfr3 was observed in colorectal carcinoma cells." (PMID 20405041, 2010). "Despite these limitations we provide first evidence that FGFR aberrations might represent potential therapeutically tractable events in a subset of colorectal cancer patients with FGFR3 mRNA overexpression being the most frequent alteration." (PMID 30181810, 2018). "These genes, along with FGFR3, appear to be co-overexpressed in colorectal cancer." (PMID 28377632, 2017). "They used several colorectal cancer cell lines to evaluate FGFR3 impact on growth and migration." (PMID 23902722, 2013). "In colorectal cancers the reciprocally downregulated receptor is FGFR3-IIIb." (PMID 22203889, 2012). "Our data show that FGFR3-IIIc exerts oncogenic functions by mediating FGF18 effects in colorectal cancer and may constitute a promising new target for therapeutic interventions." (PMID 20234367, 2010). "Moreover, disruption of FGFR3-IIIc signalling distinctly attenuated colorectal cancer xenograft growth in SCID mice." (PMID 20234367, 2010). "In colorectal cancer models, authors could not explain the loss of FGFR3 expression in human tumors since they believed that FGFR3 was an oncogene." (PMID 23902722, 2013). "However, they found, like us, a downregulation of FGFR3 expression in colorectal cancers." (PMID 23902722, 2013). "In colorectal cancer, FGFR3 transcripts are readily detected by RT–PCR; these may have escaped the nonsense-mediated decay pathway or may be the breakdown products from larger RNA transcripts, although a frame-shift means that they do not produce protein products." (PMID 14520460, 2003). "Frequently, FGFR3-IIIc expression is retained similar to the level in normal mucosa, however, which permits transduction of growth and survival signals mediated by FGF18, expression of which is upregulated in colorectal cancer." (PMID 22203889, 2012).
colorectal cancer (continued). "Furthermore, FGFR changes, especially FGFR3 overexpression are likely to occur also in more advanced colorectal cancers which we did not include in our investigation, i.e. tumors with metastases at multiple sites." (PMID 30181810, 2018). "In colorectal cancer, genomic alterations in FGFR such as gene amplifications are not as common as fusion in FGFR3 or gene copy number gain in FGFR1." (PMID 32580713, 2020).
chondrodysplasia (27 papers, 2009 to 2025). "A variety of mouse models have been generated using transgenic, Cre/loxP, and other knockin approaches to recapitulate the human phenotypes by inserting mutations associated with FGFR3-related chondrodysplasias." (PMID 40178985, 2025). "We repurposed the FGFR3 inhibitor NVP-BGJ398 to treat SLC26A2-deficient chondrodysplasias, and the treatment only partially ameliorated the phenotype." (PMID 39759111, 2025). "Genetic defects in the formation of collagen, proteoglycans, and signal transduction mechanisms such as fibroblast growth factor 3 (FGFR3) deficiency have been identified in several types of chondrodysplasias in humans." (PMID 39061550, 2024). "Among the fetuses with genetic skeletal dysplasias, 42.1% (16/38) contained variants in FGFR3, which were categorized into FGFR3 chondrodysplasia group based on the Nosology and Classification of Genetic Skeletal Disorders." (PMID 36923788, 2023). "It is well accepted that Fgfr3 gain-of-function mutations play a key role in the malformation of the skeleton in both chondrodysplasia and craniosynostosis." (PMID 37345656, 2023). "In cattle, a stop-lost variant that affects the cattle FGFR3 gene has been reported causing a dominant form of chondrodysplasia." (PMID 34925454, 2021). "Chondrodysplasia in sheep is caused by a p.Val700Glu substitution affecting the highly conserved tyrosine kinase domain ll, resulting in the loss of function of the FGFR3 gene and thereby producing skeletal overgrowth." (PMID 34925454, 2021). "It has been confirmed that fibroblast growth factor receptor 3 (FGFR3) mutations are closely related to chondrodysplasia." (PMID 32034931, 2020). "The Fgfr3Y367C mutation is one of the more strongly activating mutations of Fgfr3 causing chondrodysplasia, generating a high basal level of the downstream signaling effector, phospho-ERK." (PMID 30048539, 2018). "For example, in sheep, a missense variant in the FGFR3 gene was found to be associated with enhanced skeletal growth and meat yield when in the heterozygous state, but to induce chondrodysplasia (spider lamb syndrome) when in the homozygous state (OMIA 001703-9940)." (PMID 38424485, 2024). "Both vosoritide and infigratinib have also been evaluated in the Fgfr3Y367C/+ mouse model of FGFR3-driven chondrodysplasia." (PMID 40178985, 2025). "Taken as a whole, our results highlighted the various roles of FGFR2 and FGFR3 during endochondral bone repair and the positive action of FGFR3 antagonists in the context of fracture in FGFR3-related chondrodysplasia." (PMID 39837840, 2025). "In the present study we evaluate the efficacy of TYRA-300, a potent FGFR3-selective small-molecule TKI, in wild-type mice and 2 mouse models of FGFR3-driven chondrodysplasia." (PMID 40178985, 2025). "Studies concerning FGFR3-related chondrodysplasias have mostly focused on growth plate cartilage from birth to puberty in young animals." (PMID 37345656, 2023). "Identification of new and relevant compounds targeting the FGFR3 signaling pathway is of broad importance for the treatment of FGFR3-related chondrodysplasia." (PMID 35078974, 2022). "As an example in the first category, the FGFR3 Chondrodysplasia Group, defined by BDO/ISDS, collates bone disorders caused by a mutation in FGFR3 – hence the grouping is performed on a genetic basis." (PMID 25926964, 2015). "The aim of the present study was to examine whole gene expression changes in human pathological cartilage of FGFR3-related chondrodysplasias." (PMID 19898608, 2009). "Our study provides an example of paternal germline mosaicism in cattle as previously reported for achondrogenesis type II COL2A1‐related (OMIA001926‐9913), chondrodysplasia FGFR3‐related (OMIA001703‐9913) and osteogenesis imperfecta COL1A1‐related (OMIA002127‐9913)." (PMID 40525707, 2025).
chondrodysplasia (continued). "In the present study, we evaluated the efficacy of TYRA-300, an FGFR3 isoform–selective inhibitor that may potentially provide a larger therapeutic window, in wild-type mice and 2 mouse models of FGFR3-driven chondrodysplasia." (PMID 40178985, 2025). "The most common nosology groups in our study were the FGFR3 chondrodysplasia group (15/38, 39%), osteogenesis imperfecta and decreased bone density group (9/38, 24%), and ciliopathies with major skeletal involvement (5/38, 13%), consistent with the results of other studies." (PMID 36352425, 2022). "Genetic testing confirmed the diagnosis in the FGFR3 chondrodysplasias group." (PMID 34059710, 2021). "Abnormal mineralization, lysosomal storage disease with skeletal involvement, osteogenesis imperfecta and decreased bone density, and chondrodysplasia FGFR3 are the GSD types that may coexist with ANPMD and are frequently associated with CNS injury." (PMID 34059710, 2021).
urothelial bladder cancer (27 papers, 2013 to 2024). "FGFR3 alterations are generally associated with a lower grade and stage among all urothelial bladder carcinomas." (PMID 38392046, 2024). "Analysis of patients with bladder urothelial carcinoma in some early clinical trials and real-world studies also revealed that lower PD-L1 expression is observed in FGFR3-mutated tumors." (PMID 36966334, 2023). "The presence of FGFR3 gene alterations is generally associated with a lower grade and stage of urothelial bladder carcinoma." (PMID 36359539, 2022). "Urothelial bladder carcinoma has the most established association with altered FGFR3 signaling, with up to 80% of low-grade tumors harboring FGFR3 mutations." (PMID 34984415, 2021). "As prognostic indicators, FGFR3 gene alterations are generally associated with lower grade and stage among all urothelial bladder carcinomas." (PMID 33224141, 2020). "Activating mutations of fibroblast growth factor receptor 3 (FGFR3) are common in urothelial carcinoma of the bladder (UC)." (PMID 30952872, 2019). "As mutations in the FGFR3 regularly occur in urothelial cancer of the bladder and are amenable to targeted therapies the primary tumors and their corresponding PDX were analyzed for mutations in this gene by direct sequencing." (PMID 26041878, 2015). "Later on, critical data showed a significant association of loss of FGFR3 and tumor stage in high grade urothelial bladder cancers." (PMID 23902722, 2013). "In bladder urothelial cancer, our group and others have shown that the downregulation of miR-100 is characteristic of low-grade, non-invasive carcinomas and is thought to be an alternative pathway to the FGFR3 mutation typical of this type of tumor." (PMID 25493074, 2014). "The FGFR3 mutation is known to be frequent in UTUC, more so than in bladder urothelial cancer (35.6% vs. 21.6%)." (PMID 38137830, 2023). "FGFR3 has been validated as a prognostic and predictive marker in urothelial bladder cancer and as a therapeutic target." (PMID 36359539, 2022). "FGFR3 is a prognostic and predictive marker and is a validated therapeutic target in urothelial bladder cancer." (PMID 33224141, 2020). "In GBM, TERTp mutations coexist with EGFR amplification, and in urothelial bladder carcinoma, they are associated with FGFR3 (Fibroblast Growth Factor Receptor 3) mutations." (PMID 32204305, 2020). "Here, Faltas and colleagues report its distinctive molecular and immune landscape compared to urothelial carcinoma of the bladder and explore the role of FGFR3 signaling in UTUC biology." (PMID 31278255, 2019). "Recently, lowered expression of miR-100, resulting in upregulation of FGFR3, has been correlated with low-grade, non-invasive bladder urothelial cancer, as an alternative oncogenesis pathway to the typical FGFR3 gene mutation." (PMID 25493074, 2014). "A systematic review assessing UTUC alterations revealed significant differences between UTUC and urothelial bladder cancer, particularly in areas such as activated FGFR3 signaling, the extent of altered somatic expression of DNA mismatch repair genes, and individual UTUC molecular subtypes." (PMID 38201472, 2023). "Moreover, in bladder urothelial carcinoma with FGFR-activating mutations, FGFR3 promotes PD-L1 degradation via NEDD4." (PMID 36966334, 2023). "FGFR3 mutation has previously been linked to gene signatures of T-cell immune exclusion in urothelial bladder cancer and our observed negative correlation points towards the same direction for sq-BLCA." (PMID 36726072, 2023). "This review will summarize the current general understanding of FGFR signaling and MYC alterations in cancer, and the role of FGFR3 and MYC dysregulation in the pathogenesis of urothelial bladder cancer with the possible therapeutic implications." (PMID 39031286, 2024). "Then it focuses on FGFR3 and MYC dysregulation in urothelial bladder cancer pathogenesis as well as on the potential therapeutic implications." (PMID 39031286, 2024).
urothelial bladder cancer (continued). "Mutations in FGFR3 and PIK3CA, singly or combined with RAS and AKT1, are associated with AKT but not with MAPK pathway activation in urothelial bladder cancer." (PMID 34229750, 2021). "FGFR3 protein expression did not correlate with survival in urothelial carcinoma of the bladder." (PMID 28056982, 2017). "It is reasonable to think that the down expression of miR-100 that we previously observed in low-grade, non-invasive bladder urothelial cancer is related to the lack of control of mTOR and FGFR3 and to the maintenance of genomic stability due to not interfering with SMARCA5." (PMID 25493074, 2014).
lung adenocarcinoma (25 papers, 2013 to 2025). A carcinoma that arises from the lung and is characterized by the presence of malignant glandular epithelial cells. "Inhibition of mutant EGFR in lung adenocarcinoma cells has been shown to cause increased expression of FGFR3, and inhibition of FGFR3 was shown to block the formation of drug-tolerant cells." (PMID 38473364, 2024). "A panel of biochemical assays and functional experiments was utilized to elucidate the underlying mechanisms and effects of FGFR3 and miR-24-3p on lung adenocarcinoma progression." (PMID 29850625, 2018). "We present the first spectrum of actionable alterations in lung adenocarcinoma tumors of Indian origin, and shows that mutations of FGFR3 are present in 20 of 363 (5.5%) patients." (PMID 27998968, 2017). "We have also identified frequent and recurrent drug sensitive FGFR3 mutations in lung adenocarcinoma patients." (PMID 27998968, 2017). "We also report the first incidence of activating and drug sensitive FGFR3 mutations in lung adenocarcinoma." (PMID 27998968, 2017). "In human lung adenocarcinoma, whole genome sequencing ranked FGFR3 among the top 25 significantly mutated genes." (PMID 27056048, 2016). "Here, we show that D11 effectively inhibits signaling through FGFR3 in vitro, inhibits the growth of FGFR3-dependent FGF9-induced lung adenocarcinoma in mice, and reduces tumor-associated morbidity." (PMID 27056048, 2016). "Notably, emergence of the FGFR3::TACC3 fusion as a resistance mechanism in TKI-treated EGFR-mutated lung adenocarcinoma was associated with a tendency towards SCC-like transdifferentiation." (PMID 39387893, 2025). "Similarly, we confirmed that, in lung adenocarcinoma, miR-24-3p suppressed the expression of FGFR3 as well as some EMT-associated factors, including Snail, E-cadherin, and Vimentin." (PMID 29850625, 2018). "On the other hand, the presence of frequent FGFR3 mutations (with unknown driving potential) is tangentially referred to in the literature among Korean lung adenocarcinomas patients." (PMID 27998968, 2017). "FGFR inhibitors, which are currently in clinical testing in tumor types bearing genetic alterations in FGFR genes, may be extended to evaluate in patients with FGFR3-mutated lung adenocarcinoma." (PMID 27998968, 2017). "Along with these reports, our finding of activating FGFR3 mutations in lung adenocarcinoma patients provides an interesting convergence with mouse genetic experiments wherein activated FGF9-FGFR3 signal acts as the primary oncogenic pathway involved in initiation of lung adenocarcinoma." (PMID 27998968, 2017). "Thus, FGFR3 mutation represents an opportunity for targeted therapy in lung adenocarcinoma." (PMID 27998968, 2017). "FGF9 activates FGFR3 in the respiratory epithelium both during organogenesis and development of lung adenocarcinoma, whereas FGF7 and FGF10 signal through FGFR2b in the airway epithelium." (PMID 35675358, 2022). "While miR-24 was downregulated in both lung adenocarcinoma tissues and cells, and it suppressed the proliferation and migration of LA cells by regulating fibroblast growth factor receptor 3 (FGFR3)." (PMID 33123467, 2020). "Upregulated FGFR3 expression indicated an adverse prognosis for lung adenocarcinoma individuals and promoted metastatic potential of lung adenocarcinoma cells." (PMID 29850625, 2018). "Targeting the miR-24-3p/FGFR3 axis provides a new approach to prevent the progression of lung adenocarcinoma in clinic." (PMID 29850625, 2018). "In conclusion, these findings illustrated that FGFR3 plays crucial roles in facilitating growth and metastasis in lung adenocarcinoma." (PMID 29850625, 2018). "In accordance with the studies above, we confirmed that FGFR3 performed as an oncogene, upregulated in both tissues and cells of lung adenocarcinoma." (PMID 29850625, 2018). "In our research, we systematically analyzed FGFR3 and miR-24-3p expression in lung adenocarcinoma and identified FGFR3 as a right targeted gene of miR-24-3p." (PMID 29850625, 2018).